NUSAP1 (nucleolar and spindle associated protein 1)
Diseases named in the same sentence as NUSAP1 in open-access papers (continued):
Sharing a sentence is not in itself a finding about the gene and the disease.
cancer (continued). "Current understanding of NUSAP1’s function in specific mechanisms of cancer is limited, although some data indicates it could be a potential marker of cell proliferation." (PMID 36258196, 2022). "In accordance with our hypothesis, a number of authoritative papers have reported that NUSAP1 plays a key role in cancers including PCa." (PMID 36258196, 2022). "As a prognostic factor, NUSAP1 is abnormally upregulated in some cancers." (PMID 34782617, 2021). "In addition, NUSAP1 engages in the biological process such as cell proliferation, apoptosis, cell cycle and metastasis in several types of cancers by regulating Wnt/β-catenin, Hedgehog, PI3K/AKT, Hippo-Yap1, and other pathways." (PMID 34782617, 2021). "Accumulating evidence reveals that NUSAP1 may serve as a biomarker for carcinogenesis and cancer progression." (PMID 32226503, 2020). "In addition, NUSAP1 has been demonstrated to be involved in the development and prognosis of several cancers." (PMID 32226503, 2020). "Interestingly, it was reported that the TSPYL5 and NUSAP1 are biologically correlated with the same hallmarks of cancer: limitless replication potential." (PMID 32631280, 2020). "Taken together, these findings demonstrate that NUSAP1 may act as a cancer suppressor in the development of CESC." (PMID 32226503, 2020). "The involvement of NUSAP1 in cancer has been reported in many studies." (PMID 28899410, 2017). "In our study, high NuSAP1 expression levels indicated poor prognosis, which is consistent with the emerging role of NuSAP1 as a modulator of the relationship between the bundling of spindle microtubules and cancer." (PMID 26485712, 2015). "The involvement of NUSAP1 in cancer has been reported in many recent studies." (PMID 26554377, 2015). "NuSAP1 is upregulated and related to poor prognosis in many cancers." (PMID 26485712, 2015). "Notably, four compounds, namely MS-275 (Entinostat), 4,5-dianilinophthalimide (DAPH), W-13, and arachidonyl-trifluoromethane (AACOCF3), exhibited significantly lower scores in most cancer types, indicating their potential to inhibit pro-oncogenic effects mediated by NUSAP1." (PMID 37781040, 2023). "Since high expression of NUSAP1 is positively associated with R-loop accumulation and DNA damage, one therapeutic strategy could entail blocking DNA damage repair with poly (ADP-ribose) polymerase (PARP) inhibitors in cancers with high-level expression of NUSAP1." (PMID 37047232, 2023). "Therefore, NUSAP1 has extensive research prospects in cancer." (PMID 35739489, 2022). "The findings indicated that NUSAP1 might be involved in proliferation of the cancer cells." (PMID 28899410, 2017). "Recent studies have discovered that increased NUSAP1 expression promotes the EMT process, a critical step for cancer cells to acquire invasive and migratory capabilities." (PMID 40535133, 2025). "At the same time, NUSAP1 restricts intracellular energy homeostasis and metabolic regulation by reducing AMPK phosphorylation, thereby promoting cancer cell proliferation and metastasis." (PMID 40535133, 2025). "Subsequently, a CAF subpopulation which highly expressed cycle-related genes (CENPF, NUSAP1, and PTTG1) was annotated as proliferative CAF (prolif CAF), consistent with previous pan-cancer research." (PMID 39703515, 2024). "Cancer stage-wise expression analysis of the hub genes revealed that the expressions of TTK, BUB1B, and NUSAP1 increased while the expression of ZWINT decreased slightly with the stage-wise continued progression of OC." (PMID 37304238, 2023). "NUSAP1 appears to play a role in promoting cell proliferation and EMT in various cancer types, excluding CESC, HNSC, and STAD." (PMID 37781040, 2023). "The results revealed a negative correlation between NUSAP1 and antigen presentation-related molecules (except MICB) in most cancer types, However, in KIRC and THCA, NUSAP1 exhibited a positive correlation with the majority of immune-related molecules." (PMID 37781040, 2023).
cancer (continued). "We have previously shown that NUSAP1 is positively regulated by E2F1 and promotes cancer invasion and metastasis." (PMID 37047232, 2023). "For example, the methylation regions located in ACAA2, NUSAP1, OGFOD1, PSMD5, SNRNP40, USP37 and XRCC6 are shared by five cancers (i.e., BRCA, CESC, COAD, KIRP and SARC)." (PMID 34464378, 2021). "This suggests that HOXB2 may upregulate NUSAP1 expression through activation of the PI3K/Akt signaling pathway, consequently promoting cancer cell proliferation, invasion, and migration." (PMID 40535133, 2025). "Interestingly, its corresponding mRNA, NUSAP1, is also increased in HCC, enhances the stemness of cancer cells, and promotes early cancer recurrence." (PMID 40003874, 2025). "Therefore, to the best of our knowledge, this study is the first to report the probable cancer-driving role of the hsa-mir-124-3p miRNA with respect to TTK, BUB1B, NUSAP1, and ZWINT hub genes in OC." (PMID 37304238, 2023). "This potential mechanism may explain the inhibitory effect of NUSAP1 observed in HNSC and other cancer types." (PMID 37781040, 2023). "To investigate whether NUSAP1 expression can influence the immune cell infiltration in human cancers, we first analyzed the ESTIMATE database to compare immune scores between NUSAP1-high and NUSAP1-low expressing patients in 18 cancer types." (PMID 37781040, 2023). "Likewise, increased expression of NUSAP1 and ILF2 are correlated with higher Gleason scores of cancer, the most important clinical predictor of recurrence." (PMID 37047232, 2023). "Furthermore, NUSAP1 exhibited an inverse expression pattern between T-proli and exhausted CD8+T cells in multiple cancer tissues, suggesting its potential regulatory role in T cell function." (PMID 37781040, 2023). "To investigate the prognostic impact of NUSAP1 mRNA levels in human cancers, we downloaded and analyzed curated survival data from the UCSC database, including OS, DSS, DFI, and PFI for 31 different cancer types." (PMID 37781040, 2023). "Notably, we also found a cluster of cells that exhibited higher expression of a set of cell cycle-related genes (CENPF, NUSAP1, PTTG1, STMN1, TOP2A, and TUBA1B), which was consistent with proliferative CAFs (pCAFs) in a previous pan-cancer study of CAFs." (PMID 37833788, 2023). "Furthermore, the MAP of mitosis bio-function predicted it as inhibited because of the downregulation of NUSAP1 and AURKA that directly modified this critical process in cancer development." (PMID 36478748, 2022). "Moreover, QSOX2 silencing in NSCLC cell lines resulted in inhibition of cancer cell proliferation, induction of apoptosis, and decreased expression of cell division-related genes (CENPF and NUSAP1) and Wnt pathway activators (PRRX2 and Nuc-β-catenin)." (PMID 34350181, 2021). "In addition, a negative correlation was observed between high NUSAP1 levels and immune cell infiltration into tumors, as well as the expression of antigen presentation-related molecules in most cancer types." (PMID 37781040, 2023). "However, a negative correlation was observed between high NUSAP1 levels and immune cell infiltration into tumors (Step 5) in most cancer types, further indicating the immunosuppressive effect of NUSAP1 in TME." (PMID 37781040, 2023). "Interestingly, the enrichment of the EMT pathway was not significant in HNSC and STAD patients with high NUSAP1 levels, consistent with the analysis of N and M status in these two cancers." (PMID 37781040, 2023). "However, there has been a lack of systematically comprehensive pan-cancer studies conducted to explore the predictive value of NUSAP1 for prognosis and immunotherapy response." (PMID 37781040, 2023).
cancer (continued). "Overexpression of NUSAP1 and ILF2 are both upregulated in cancer compared to non-cancerous prostate tissues and both correlate with an increased risk of recurrence after surgery." (PMID 37047232, 2023). "We propose that increased expression of NUSAP1 and ILF2 drive progression, at least in part through their effects on R-loops and DNA damage; however, it is possible that this is not the major pathway through which these proteins increase cancer aggressiveness." (PMID 37047232, 2023).
infection (2 papers, 2017 to 2023). The state of being infected such as from the introduction of a foreign agent such as serum, vaccine, antigenic substance or organism. "Knockdown of NUSAP1 expression in DU145 or PC-3 cells stably using two different shRNAs to NUSAP1 versus scramble shRNA control was performed for 72 or 96 hours post initial infection." (PMID 28404898, 2017). "To gain insights into gene expression alterations induced when NUSAP1 is modulated, we used lentiviral infections to overexpress or knockdown NUSAP1 in DU145 or PC-3 cells for 72 or 96 hours, verified overexpression or knockdown by RT-qPCR and western blot, and performed RNA sequencing (RNA-Seq)." (PMID 28404898, 2017).
digestive system cancer (1 paper, 2025). A primary or metastatic malignant neoplasm involving any part of the digestive system. "However, whether GSK-3B inhibition potentiates NUSAP1 activity in digestive system cancers remains experimentally unexplored." (PMID 40535133, 2025).
digestive system tumors (1 paper, 2025). "Further analysis using COX risk regression and the construction of prognostic models have demonstrated that the overexpression of NUSAP1 is associated with poor prognosis in digestive system tumors." (PMID 40535133, 2025). "Future research should aim to investigate the associations and common mechanisms of NUSAP1 across different digestive system tumors." (PMID 40535133, 2025). "In summary, as research on NUSAP1 and digestive system tumors continues to deepen, the importance of NUSAP1 in various malignant biological behaviors of tumors has become increasingly apparent." (PMID 40535133, 2025). "Based on the preceding analysis, it is evident that NUSAP1 serves as an important mediator in the miRNA-regulated progression of digestive system tumors." (PMID 40535133, 2025). "This article primarily reviews the structural characteristics, functional mechanisms, and related signaling pathways of NUSAP1, focusing on exploring the functional mechanisms of NUSAP1 in digestive system neoplasms." (PMID 40535133, 2025). "Consequently, NUSAP1 holds significant potential for research in specific therapies (such as chemotherapy, radiotherapy, and immunotherapy), efficacy evaluation, postoperative surveillance, and prognosis in patients with digestive system tumors." (PMID 40535133, 2025). "Additionally, targeted therapies aimed at NUSAP1 may provide more promising treatment options for patients with digestive system tumors." (PMID 40535133, 2025).
NUSAP1 also shares sentences with these, for which no sentence is quoted: non-small cell lung carcinoma (4 papers); esophageal squamous cell carcinoma (3); breast-invasive carcinoma (2); invasive ductal carcinoma (2); pituitary adenomas (2); Alzheimer disease (1); anaplastic astrocytoma (1); anaplastic thyroid carcinoma (1); benign brain tumor (1); Crohn disease (1); development (1); ductal carcinoma in situ (1); endometrial cancer (1); endometrioid carcinoma (1); gastric tumors (1); gestational diabetes mellitus (1); glomerulonephritis (1); Huntington disease (1); hypopharyngeal squamous cell carcinoma (1); IgA nephropathy (1); kidney chromophobe (1); large cell lung cancer (1); liver cirrhosis (1); lung diseases (1); malaria (1); malignant glioma (1); malignant pleural mesothelioma (1); meningioma (1); metabolic dysfunction-associated steatohepatitis (1); microcephaly (1).
A further 7 diseases each share a sentence with NUSAP1 in 1 paper.